FAP (fibroblast activation protein alpha)
Diseases named in the same sentence as FAP in open-access papers (continued):
Sharing a sentence is not in itself a finding about the gene and the disease.
tumor (continued). "[68 Ga]Ga-FAPI-46 PET/CT is a promising molecular imaging method, which targets the overexpression of fibroblast activation protein (FAP) in the cancer associated fibroblasts of the tumor microenvironment and has been assessed in various tumor entities." (PMID 38236427, 2024). "Fibroblast activation protein-alpha (FAP) is overexpressed in CAFs in >90% of human tumor tissues, and exosome-like nano-vesicles derived from tumor cells with FAP mutations (eNVs-FAP) have been developed." (PMID 38835784, 2024). "Eleven studies (two prospective, one retrospective, and eight case reports) have compared the diagnostic performances of FAP-specific radiopharmaceuticals against other tracers in patients with various neoplasms." (PMID 39000301, 2024). "One such barrier is the protease fibroblast activation protein (FAP), expressed by many tumor-associated stromal fibroblasts, which plays a crucial role in remodeling the tumor ECM." (PMID 39134804, 2024). "FAP is overexpressed by cancer-associated fibroblasts present in the tumor microenvironment, which leads to high tumor uptake and very low accumulation in normal tissues, achieving excellent results." (PMID 36831405, 2023). "We aimed to assess prevalence, distribution, and intensity of in-vivo arterial wall fibroblast activation protein (FAP) uptake, and its association with calcified plaque burden, cardiovascular risk factors (CVRFs), and FAP-avid tumor burden." (PMID 37147478, 2023). "Upon several cases, elevated FAP expression is associated with greater tumor size, advanced clinical stage and lymph node metastases." (PMID 37166418, 2023). "FAP overexpression increases the risk of tumour invasion, lymph node metastasis and the decreased overall survival (OS) of many solid cancers, including mCRPCa, especially if the cancer exhibits neuroendocrine (NE) differentiation." (PMID 36980482, 2023). "Generally, FAP can cause tumor progression and metastasis; however, this review will specifically discuss FAP functions in CRC." (PMID 37316886, 2023). "In the initial phases of the assessment of the disease, the visualization of the FAP through radio-diagnostic techniques allows a better perception of the three-dimensionality of the neoplasm and consequently allows a better staging." (PMID 37892020, 2023). "In practice, the necessity of long time and dynamic observation on FAP expression, especially on the tumor-associated fibroblasts, stands to reason due to the proven relationship between FAP and prognosis, as well as the development of dual-phase examinations." (PMID 36986521, 2023). "One study found that FAP-specific CAR T-cells demonstrated minimal anti-tumor activity and caused bone toxicities due to expression of FAP on bone marrow stromal cells." (PMID 38201551, 2023). "Fibroblast activation protein α (FAP-α) is a cell-surface protein overexpressed on cancer-associated fibroblasts that constitute a substantial component of tumor stroma and drive tumorigenesis." (PMID 37110717, 2023). "Fibroblast activation protein (FAP) is a membrane-bound peptidase, which is overexpressed on cancer-associated fibroblasts (CAFs) in the tumour microenvironment." (PMID 37631053, 2023). "Fibroblast activation protein (FAP) is highly expressed on cancer-associated fibroblasts (CAFs) and various tumor cells, playing an important role in tumor growth and immunosuppression." (PMID 38102692, 2023). "FAP expression is associated with worse prognosis as FAP supports tumor migration, angiogenesis, metastasis via matrix remodeling in TME, and immunomodulatory function." (PMID 36770755, 2023). "IHC evaluation in consecutive sections of CRC tumors performed by expert pathologist indicated that POSTN and FAP were expressed by tumor-associated fibroblasts, thus corroborating the POSTN expression by CRC CAFs reported in previous studies." (PMID 36765091, 2023).
tumor (continued). "The first is intended to localize CD137 agonistic activity to FAP+ tumor-associated macrophages (TAM) to preferentially activate T cells in the TME." (PMID 36793863, 2023). "We also detected higher expression levels of EIF4A3 in FAP (+) tumor-associated fibroblasts, indicating a potential link between the tumor microenvironment and EIF4A3." (PMID 37777564, 2023). "The presence of CAFs and FAP expression have been reported to be strongly associated with metastasis and poor prognosis in various tumor types, making FAP a suitable target for tumor imaging and therapy." (PMID 37835533, 2023). "The broad spectrum of fibrotic disease and particularly involvement in cancer rendered FAP a potential target for oncology imaging and therapy targeting tumor-associated fibroblasts." (PMID 37126137, 2023). "Fibroblast activation protein (FAP), expressed on cancer-associated fibroblasts, is a target for diagnosis and therapy in multiple tumour types." (PMID 37408254, 2023). "FAP is expressed by cancer-associated fibroblasts (CAFs), and its expression is associated with high tumor proliferation, decreased survival, and worse prognosis in cancer patients." (PMID 36832085, 2023). "Concluding from the evidence and findings gained from the studies about the expression of FAP in CRC tumor samples and its association with prognosis." (PMID 37316886, 2023). "FAP inhibitor (FAPI), which has recently attracted attention as a cancer-targeting molecule, causes the accumulation of FAP, which is overexpressed in the tumor stroma and is involved in cancer growth." (PMID 37240044, 2023). "If this finding is true and can be verified in independent studies, it would contradict findings in other tumor types where FAP overexpression is associated with an increase in the tumor’s aggressiveness." (PMID 37727209, 2023). "Histopathology and FAP immunohistochemistry (IHC) of initial diagnostic biopsy and resected tumor samples will serve as the truth standards." (PMID 38011131, 2023). "They then used flow cytometry to demonstrate that a portion of these FAP+CD45+ cells were CD11b+CD14+MHC−II + tumor associated macrophages." (PMID 38196606, 2023). "Many studies have demonstrated that FAP is expressed by the cancer-associated fibroblasts (CAFs) that occupy the tumor microenvironment (TME), and is overexpressed in 90% of epithelial tumors, including colon and breast cancers." (PMID 36770755, 2023). "The variables taken into consideration are BRAF, KRAS, NRAS mutations, the expression of fibronectin, CXCR4, and FAP in terms of intensity in both the primary tumor and metastases, and the number of metastases." (PMID 37892020, 2023). "FAP, being a specific marker of tumor-associated fibroblasts, demonstrates variable expression levels across different cancer types and predicts diverse, and at times contradictory, prognoses among cancer patients." (PMID 37490719, 2023). "FAP-positive cancer associated fibroblasts (FAP+ CAFs) recruit macrophage infiltration into the tumor microenvironment and thus shape the immune suppression landscape." (PMID 37166418, 2023). "Fibroblast activation protein (FAP), a type II transmembrane glycoprotein, is expressed by cancer-associated fibroblasts (CAFs) that form a major component of the tumor stroma." (PMID 37370912, 2023). "In the meantime, FAP is present in a broad range of tumors and its variability is linked to the effectiveness of tumor therapies." (PMID 38706713, 2023). "FAP is overexpressed particularly in epithelial malignancies exhibiting rapid tumor growth and proliferation, and thus expression is linked to a poor prognosis." (PMID 37345133, 2023). "By secreting CCL-2, IL-6, and CXCL8, FAP+ CAF-like cells are able to induce macrophages differentiation into tumor-associated macrophages." (PMID 37166418, 2023).
tumor (continued). "In the context of malignant pleural mesothelioma (MPM), a devastating disease resulting from exposure to asbestos, FAP expression on reactive tumor-associated fibroblasts makes it an attractive target for adoptive T-cell therapy using CARs." (PMID 38516299, 2023). "In the current study, the potential diagnostic value of serum FAP detection as a marker was investigated in conjunction with tumor images." (PMID 37864148, 2023). "Fibroblast-Activation Protein-α (FAP) is a type II transmembrane cell surface proteinase expressed on the surface of cancer-associated fibroblasts in tumor stroma." (PMID 37316886, 2023). "The presence of FAP-expressing CAFs is crucial in tumorigenesis and development, and their depletion is associated with tumor shrinkage." (PMID 38706713, 2023). "Fibroblast activation protein (FAP)-expressing Cancer-Associated Fibroblasts (CAFs) are crucial components of the tumor stroma, influencing carcinogenesis, fibrosis, tumor growth, metastases, and treatment resistance." (PMID 38011131, 2023). "[68Ga]Ga-FAPI-46 is a novel PET ligand that targets the fibroblast activation protein (FAP), which can be overexpressed in tumor-associated fibroblast in the tumor microenvironment." (PMID 37111363, 2023). "Several studies have indicated that FAP expression is associated with a shift in immune cell populations within the tumor, thereby promoting a pro-tumorigenic environment." (PMID 37614665, 2023). "By activating signal transducer and activator of transcription 3 (STAT3), which is an important transcription factor in tumor-associated inflammation, FAP has been shown to mediate the inflammatory effects of CAFs." (PMID 38313431, 2023). "This study analyzed the clinical significance of a canonical CAF marker, FAP, in pretreatment tumor specimens to determine its association with T cell infiltration and immunotherapy outcomes in advanced NSCLC." (PMID 35951090, 2023). "Nonetheless, the circulation time of FAP inhibitors is relatively short, resulting in rapid clearance via kidneys, low tumor uptake, and associated unsatisfactory treatment efficacy." (PMID 38706713, 2023). "Overall, a high degree of FAP expression is associated with tumor aggressiveness and poor prognosis." (PMID 37370912, 2023). "For a long time, FAPα has been mentioned only as a marker of cancer-associated fibroblasts (CAFs), which are an essential component of tumor stroma." (PMID 38136590, 2023). "Not only can FAP facilitate an immunosuppressive environment that promotes tumor growth and metastasis, but it can also cause the tumor to be more resistant to therapies." (PMID 37892020, 2023). "Fibroblast activation protein‐α (FAP) and livin α are considered as cancer‐associated fibroblasts (CAFs) and tumor‐specific targets, respectively, for immunogenic tumor vaccines." (PMID 37773704, 2023). "Gene enrichment analysis demonstrates that ECM-receptor interaction as well as extracellular matrix and structure process are linked to the potential mechanism of FAP in tumor pathogenesis." (PMID 37166418, 2023). "Due to their close association with tumor progression, metastatic spread and treatment resistance, CAFs and, in turn FAP, are recently emerging as promising targets for cancer diagnosis and treatment." (PMID 36765866, 2023). "Despite these challenges, there is still value in targeting FAP-positive CAFs in the tumor-associated stroma." (PMID 38516299, 2023). "A positive association was noted between FAP expression in the tumor center and poor prognosis (multivariate hazard ratio, HR = 1.72, p-value = 0.025)." (PMID 37316886, 2023). "In CKP mice, both antibodies accumulated in the tumor, buttumor-to-blood ratios of 28H1-700DX were higher than that of the control.Notably, in vivo FAP-tPDT caused upregulation of cleaved caspase-3staining in both subcutaneous and in spontaneous tumors." (PMID 37485886, 2023).
tumor (continued). "We surprisingly find that FAP expression level is remarkably related to the infiltration of tumor-associated fibroblasts, macrophages, myeloid dendritic cells, endothelia cells as well as hematopoietic stem cells in most types of cancers." (PMID 37166418, 2023). "In summary, the analysis of FAP expression across various cancer types revealed a strong association between FAP upregulation and clinical outcomes, tumor diagnosis, DNA methylation levels, and immunotherapy responses." (PMID 37490719, 2023). "Both biomarkers, SPARC and FAP, are associated with tumor progression and metastasis and predict a poor outcome in patients with PDAC." (PMID 38136299, 2023). "[68Ga]Ga-FAPI-46 is a radiolabelled fibroblast activation protein inhibitor that selectively binds to fibroblast activation protein (FAP), which is overexpressed by cancer-associated fibroblasts (CAFs) in the tumour microenvironment." (PMID 37631053, 2023). "Unlike many clinically available tracers that directly target tumor cells, the imaging of the fibroblast activation protein (FAP) allows for the detection of cancer-associated fibroblasts (CAFs)." (PMID 37835533, 2023). "FAP-IL2v is an immunocytokine comprising an antibody against FAP and an IL-2 variant, and FAP-IL2v demonstrated ability of targeting tumor according to imaging studies results." (PMID 37055382, 2023). "Undoubtedly, the data also suggested that FAP was involved in specific functions of certain tumor, for instance, FAP is also associated with digestion function in PAAD." (PMID 37325617, 2023). "Within a subgroup of STS, heterogeneity of FAP expression can be caused by factors such as the tumor grade or preoperative treatment." (PMID 37727209, 2023). "Tumor-associated macrophage markers (CD163), tumor-associated fibroblast markers (FAP), and epithelial-mesenchymal transition (EMT) were detected by western blot." (PMID 37907991, 2023). "Targeting FAP-positive cells with a monoclonal antibody linked with a cytotoxic drug showed an effective inhibition of tumor growth in mice models of lung, pancreas, and head and neck cancer." (PMID 37046710, 2023). "FAP is expressed by predominantly cancer-associated fibroblasts in the stroma of various tumor entities, leading to highly tumor-specific expression." (PMID 37024301, 2023). "Fibroblast activation protein (FAP) is one of the most investigated tumor-associated antigens expressed in the stroma of most tumor types whilst being almost undetectable in normal tissue." (PMID 37092450, 2023). "Our study highlights that tumor-associated fibroblasts (especially FAP + and MFAP5 + fibroblasts) can secrete MIF, which binds to the corresponding receptor CD74 on macrophages to drive immunological escape." (PMID 37344903, 2023). "A higher degree of FAP expression is associated with higher tumor grade, invasiveness, and poor prognosis in CRC." (PMID 37370912, 2023). "Most of FAP's functions have been linked to its enzymatic activity in tissue remodeling, which aids tumor cells in invading surrounding tissue, breaking through the wall of blood vessels, and traveling to form distant metastases." (PMID 37316886, 2023). "FAP expression was also assessed in 112 GC tumor specimens, and it was revealed that 62.5% of patients had high FAP expression associated with primary tumor invasion and high TNM stage." (PMID 37316886, 2023). "At the same time, low-expression level of MYB was detected in FAP (+) tumor-associated fibroblasts by microarray." (PMID 36994664, 2023). "Radioligand diagnostic and therapeutic products targeting FAP in the tumor microenvironment represent a promising class of compounds with pan-tumoral applicability and high selectivity for tumor lesions." (PMID 36015106, 2022). "The fibroblast activation protein (FAP) is heavily expressed in fibroblasts associated with the tumor microenvironment, while the prostate-specific membrane antigen (PSMA) is expressed in the neovasculature of malignant angiogenic processes." (PMID 36500804, 2022).
tumor (continued). "In cancer, FAP overexpression is associated with high tumor stage/grade, lymph node invasion, recurrence and reduced patient survival." (PMID 35163938, 2022). "FAP overexpression and cancer associated fibroblasts (CAFs) found in tumor stroma are believed to cause the FAP-positive signaling in extracranial tumors." (PMID 36566187, 2022). "FAP represents a transmembrane glycoprotein expressed on cancer-associated fibroblasts (CAFs) of several tumor entities." (PMID 36171444, 2022). "FAP is overexpressed in cancer-associated fibroblasts in the tumor stroma of several types of cancers, including breast, colon, and pancreatic carcinomas." (PMID 35565232, 2022). "Meanwhile, GPX8 mRNA expression was significantly correlated with monocyte marker CD14, dendritic-cell marker NRP1, natural killer cell marker B3GAT1, neutrophil marker CCR7, and tumor-associated fibroblast marker FAP." (PMID 36061208, 2022). "Fibroblast activation protein (FAP) is highly expressed on cancer-associated fibroblasts in the tumor stroma and at very low expressed levels throughout the body." (PMID 36051919, 2022). "The presence of CAFs within the tumor, quantitatively depicted as FAP positivity, was strongly linked to the expression of MMP13, AKT1, TGFB3 and TGFBR2, among other factors." (PMID 35311102, 2022). "The underlying mechanism of the inhibited tumour growth is that the FAP‐CAR‐T cells disrupted the ECM, allowing for more endogenous CD8+ T cell antitumor responses from host immunity." (PMID 36495108, 2022). "An observed high expression of FAP in UVM tumor tissues was associated with poor patient prognosis and reduced promoter methylation in the FAP gene." (PMID 35186170, 2022). "Fibroblast activation protein (FAP) is highly expressed on the cancer-associated fibroblasts (CAF) of the tumor stroma." (PMID 35745648, 2022). "FAPα is selectively expressed in tumor pericytes or cancer-associated fibroblasts (CAFs), which facilitates extracellular matrix remodeling, immunosuppression, and angiogenesis and subsequently promotes tumor progression and metastasis." (PMID 35951441, 2022). "FAP, a proline-selective serine protease, is overexpressed in hypertrophic/KS tissue and the tumor stroma (cancer/tumor-associated fibroblasts, CAFs/TAFs) but undetectable in most normal adult tissues." (PMID 36092734, 2022). "It has been shown that FAP is overexpressed in tumor-associated stromal cells of epithelial tumors and its expression is related to advanced stages, worse prognosis, and poor survival." (PMID 36479116, 2022). "In conclusion, our results showed that FAP expression in tumor cells and the combination of FAP expression in tumor cells and CAFs was strongly associated with patient survival." (PMID 35818720, 2022). "This study aimed to explore the role of FAP in STAD and the underlying association between FAP and the tumor microenvironment (TME) and ferroptosis." (PMID 35359436, 2022). "Fibroblast activation protein (FAP) is a type II transmembrane serine protease that is overexpressed in cancer-associated fibroblasts (CAFs), and plays a key role in modulating the tumor microenvironment, angiogenesis, and chemotherapy resistance." (PMID 35903277, 2022). "Fibroblast activation protein (FAP) is strongly expressed on cancer-associated fibroblasts and is a key player in tumor progression." (PMID 34740953, 2022). "Multiple studies report FAP specific CAR-T cells cause an inhibition of tumour growth in multiple mouse models that was dependent on the immune response." (PMID 35479076, 2022). "FAP expression is associated with aggressive tumor features and clinical course including progression and metastasis." (PMID 35052475, 2022). "In cancer indications of mesenchymal origin, notably sarcoma and mesothelioma, FAP is expressed on the tumor cells in addition to cancer-associated fibroblasts." (PMID 34168013, 2022).